CXCL9 (C-X-C motif chemokine ligand 9)
Diseases named in the same sentence as CXCL9 in open-access papers (continued):
Sharing a sentence is not in itself a finding about the gene and the disease.
tumor (continued). "As IFN-γ diffusion was restricted in OC, CXCL9/10 concentration decreased, which facilitated “cold” tumor phenotypes by limiting T-cell infiltration." (PMID 36618371, 2022). "CD8+ T cells express CXCR3 and are recruited into the tumor by the CXCR3 ligands CXCL-9, CXCL-10, CXCL-11." (PMID 36611932, 2022). "In vitro migration studies underlined that low concentrations of CXCL9 and CXCL10 produced by tumor endothelial cells promoted chemotaxis." (PMID 35626062, 2022). "CCL5 is produced by tumor cells, while CXCL9 is produced by TAMs and DCs, which are dependent on antigen recognition and IFN-γ-specific induction." (PMID 35892835, 2022). "The capacity to induce CXCL9 in the tumour microenvironment should thus be an eligibility criterion to efficiently select ICB therapy partners in the future." (PMID 35314795, 2022). "When the expression of Rantes in tumor cells decreased, the expression of CXCL9 also decreased, leading to decrease in the number and exhaustion in the function of CD8+ T cells in the TME." (PMID 35892755, 2022). "A significant reduction in cell proliferation as determined by Ki-67 positivity was induced by ICB treatment in Cxcl9+ tumours (median 15.3% vs. 30.3%; P = 0.002)." (PMID 35314795, 2022). "Meanwhile, one investigator found in a mouse model that CXCL9 expressed by tumor cells suppressed local tumor growth and metastasis by recruiting host NK cells and a large number of CXCR3+CD4+ and CXCR3+CD8+ host T cells." (PMID 36479091, 2022). "For example, tumor CXCR3 and tumor-draining lymph node CXCL9 and CXCL10 promote the metastasis of murine melanoma cell line B16F10." (PMID 35216243, 2022). "Among the chemokines known to attract CD8+ T cells into the tumor are CXCL9, CXCL10, and CXCL11, all of which bind to the chemokine receptor CXCR3 expressed at the surface of CD8+ T cells." (PMID 35439168, 2022). "Then, we compared the expression of IFNβ and CXCL9 in tumor derived leukocytes from WT and STING-/- mice." (PMID 35623658, 2022). "For instance, EZH2, a histone 3 lysine 27 trimethylation regulator, mediates epigenetic silencing of tumor CXCL9 and CXCL10, two Th1-type chemokines, and consequently represses effector T cell trafficking into the tumor microenvironment." (PMID 35664070, 2022). "The results of tumor purity showed that three cytokines (CCL5, CCL19 and CXCL9) were negatively correlated with tumor purity, which indicated that tumor cells were reduced but immune cells increased in tissues with high expression of these cytokines." (PMID 35359417, 2022). "Nanostring nCounter IO 360 analysis indicated that RXC004 significantly increased the overall tumor-associated CD45+ immune cells, including dendritic cells, and increased tumor expression of the chemokine CXCL9 in this B16F10 model." (PMID 36922934, 2022). "The majority of the tumor supernatants (91.2%) had high CXCL9 levels, compared to their juxta-tumor counterparts." (PMID 36539890, 2022). "These three modules contained recognized immune-related genes, such as CD86 and CD226, which have been reported to increase the downstream activation of NF-κB and CXCL9 whose secretion recruited CD8+ T cells into the tumor bed." (PMID 35237300, 2022). "In vivo, Cxcl9 concentration was significantly higher in the ascites of Brca2−/−Cxcl9+ tumours than in the ascites of Brca2−/−Control tumours (median 3.0 vs. 1.6 pg/mL; P = 0.033)." (PMID 35314795, 2022). "G3-C12@PLGA not only maintained CXCL9/10 concentrations in tumor tissues for a long time by releasing IFN-γ and continuously recruiting CD8+ T cells into tumors, but also helped anti-PD-1 peptide to function better." (PMID 36618371, 2022). "A recent study of whole-exome and transcriptome data from more than 1000 bulk tumor tissues of 7 cancer types that were treated with ICIs reported that CXCL9 expression was one of the strongest predictors of a therapeutic response." (PMID 35389889, 2022).
tumor (continued). "Mechanistically, we observed that the coculture with MRTX-treated tumor cells was able to lead to the up-regulation of CXCL9 in DCs in vitro." (PMID 35857848, 2022). "At the primary tumour site, we found that Gzmb, Ifng, and Cxcl9 transcripts were significantly reduced in carcinogen-induced Stat1−/− compared to Stat1+/+ mice." (PMID 35595823, 2022). "Consistently, a recent report identified CXCL9 gene expression as the most powerful marker besides TMB to predict ICB response in >1000 patients across multiple tumour types." (PMID 35314795, 2022). "Compared with the normal compartments, the CXCL9 protein level in the tumor showed little difference but increased ~8 fold after I.T. vaccination." (PMID 35623658, 2022). "IFN-γ plays an important role in regulating the tumor immune microenvironment by inducing the production of CXCL9." (PMID 36566226, 2022). "In human solid tumors, CCL5 expressed by tumor cells and CXCL9 expressed by both macrophages and DCs are important for tumor infiltration by T cells, a process that also involves the identification of tumor antigens by T cells." (PMID 36387070, 2022). "The chemokine CXCL9 plays an important role in the inflammatory process and angiogenesis and is also related to the occurrence, development and metastasis of tumours." (PMID 35292033, 2022). "Enhancer of zeste homolog 2 (EZH2), a PRC2 component, mediates histone H3 lysine 27 trimethylation and represses tumor production of CXCL9 and CXCL10." (PMID 34385592, 2022). "Together, these data indicate that Activin-A expression in tumor interferes with CTL recruitment by attenuating the expression of CXCL9 in MoMac and DCs." (PMID 35580932, 2022). "These activated immune cells release interferon γ (IFN-γ), which in turn activates macrophages and dendritic cells that cluster in the tumor to secrete CXCL9, which further promotes the infiltration of circulating T cells into tumor tissue." (PMID 35892755, 2022). "It is already known that CXCR3 is primarily expressed on vascular cells, NK cells, tumor cells, and activated T lymphocytes and binds to CXCL9 to CXCL11." (PMID 35978426, 2022). "These transcriptional changes also led to increased protein expression of ISG, as evidenced by an increased proportion of IFNγ-induced CXCL9-secreting tumor cells after treatment with MRTX." (PMID 35857848, 2022). "Lysates of MTX-treated 9464D tumors displayed a more than 2.5-fold increase of IL1a, CXCL16, FLT3L, CX3CL1 and IL1RA, and a more than 1.5-fold increase of CXCL10, CXCL5, CCL5 and CXCL9 compared to control tumor lysates." (PMID 36397148, 2022). "T-cell migration into the tumour microenvironment depends on the local production of specific chemokines, especially CXCL9 and CXCL10, which engage CXCR3 on the surface of CD8+ effector T cells." (PMID 36376335, 2022). "CXCL9 is upregulated in chemotherapy-sensitive patient tumors and increases T-cell infiltration, tumor control, and patient survival." (PMID 36566226, 2022). "Cyclin G2 inhibited tumor angiogenesis and promoted the recruitment of CTLs by increasing the release of CXCL9 from macrophages." (PMID 36566226, 2022). "further suggested that the interaction of CXCR3-A (expressed on tumor cells) with CXCL-9 promotes tumor metastasis through activation of the phosphatidylinostol 3-kinase (PI3K) and mitogen-activated protein kinase (MAPK) signaling pathways." (PMID 36389701, 2022). "It has been shown that CXCL9 can inhibit tumor growth by mediating lymphocyte infiltration to the lesion site." (PMID 36704353, 2022). "The tumor-infiltrated B cells secrets a high amount of CXCL9 that commits the T CD8 cells to the tumor milieu." (PMID 35632488, 2022). "CXCL9 has been reported to be involved in various pathological processes, including tumor development, immunity, and inflammation." (PMID 35514751, 2022).
tumor (continued). "It has also been reported that increased levels of CXCL9/10 were associated with increased numbers of tumor-infiltrating CD8+ T cells and CXCL9/10 were related with efficiency of immune therapy by blocking PD-L1 and PD-1 interaction." (PMID 35359417, 2022). "At the same time, many experts have discovered that CXCL9 under-expression significantly impairs the immune cell-mediated anti-tumor immune response." (PMID 36479091, 2022). "Targeting TAMs to produce pro-inflammatory cytokines, such as IFN-γ and TNF-α, can promote an immune-favorable microenvironment while also producing T cell-specific chemokines, such as CXCL9, to recruit T cells to the tumor." (PMID 35513776, 2022). "On the other hand, deletion of PTPN11 enhances macrophage response to IFN-γ and increases production of the tumor cell-derived cytokine CXCL9, thereby promoting tumor infiltration of IFN-γ-producing T cells." (PMID 35957898, 2022). "Tumor mutation burden (TMB) had weak positive correlations only with CD274 (p = 0.01342; R = 0.127), CXCL9 (p = 0.038; R = 0.1078), and also with the XP cluster 2 genes ERCC3 (p = 0.00196; R = 0.157) and ERCC2 (p = 0.027; R = 0.114)." (PMID 35174087, 2022). "IHC staining of tumor tissues from mice treated with B3GALT4 knockdown 9464D cells confirmed the expression levels of CXCL9 and CXCL10, and the percentage of CD8A-positive cells was increased after MβCD treatment, while caveolin-1 was decreased." (PMID 36284313, 2022). "CXCL9, 10, and 11 are mainly secreted by monocytes, endothelial cells, fibroblasts, and tumor cells." (PMID 36479091, 2022). "Previous studies have shown that tumor infiltration of activated T cells and NK cells is significantly reduced in mice deficient in CXCR3, the receptor for CXCL9 and CXCL1032." (PMID 36266311, 2022). "For example, epigenetic silencing of CXCL9/10 expression by promoter DNA methylation and H3K27me3 in tumor cells limits the infiltration of cytotoxic T cells, preventing tumor attack and promoting tumor growth." (PMID 36221123, 2022). "In a previous study, CCL5 was found to interact with CXCL9 expressed by macrophages, leading to an increase in T cell infiltration and inhibition of tumor progression." (PMID 36428599, 2022). "Ki-67 positivity was identical in Cxcl9+ and Control tumours (median 32.6% vs. 30.6%; P = 0.52), confirming our in vitro results, thus excluding changes in cell proliferation by Cxcl9." (PMID 35314795, 2022). "CXCL9, which is referred to as monokine induced by gamma IFN (MIG), primarily mediates lymphocyte infiltration into the lesion site and inhibits tumor growth." (PMID 35702353, 2022). "The loss of PTPN2 results in an increase in tumor antigen presentation and T-cell trafficking due to enhanced expression of IFNγ-responsive genes, including MHC-I, Cxcl9, Cxcl10, Cxcl11, and Ccl5." (PMID 34385592, 2022). "In the previous study, the co-expression of CCL5 and CXCL9 has been detected to reveal immunoreactive tumours with prolonged survival and response to PD-1 inhibition." (PMID 35865633, 2022). "CXCL9, CXCL10, and CXCL11/CXCR3 are anti-tumor angiogenic factors, and the inhibition of tumor angiogenesis can be achieved via upregulating the expression of CXCL9, CXCL10, and CXCL11." (PMID 35770088, 2022). "CXCL9, CXCL10, CXCL11, and CXCR3 recruited and activated immune cells, such as CD8 + T-cells, to suppress tumor progression through CXCL9,-10−11/CXCR3 axis, and they were down-regulated in the high-GATA3 group." (PMID 35647011, 2022). "Fourth, despite the impressive promotion in tumor immunity, the roles of the four chemokines-CXCL9, CXCL10, CXCL11, and CCL5-in tumorigenesis and progression were still in debates." (PMID 35692828, 2022). "Another myeloid cell-secreted chemokine CXCL9 correlates the engraftment of tumor-infiltrating lymphocytes and amplifies the anti-tumor response of cytotoxic T lymphocytes." (PMID 35145917, 2022).
tumor (continued). "By releasing an extracellular regulator, galectin-3, tumor cells are capable of blocking interferon gamma (IFN-γ) in the TME followed by impeding chemokines CXCL9, CXCL10, and CXCL11 leading to obstructed T-cell recruitment into the tumor bed." (PMID 35053449, 2022). "DCR following treatment was 71%, in association with improved IFNγ production, CXCL9/CXCL10 chemokine expression and increased intra-tumor T cell infiltration, all representative of an immune-stimulatory environment." (PMID 36428727, 2022). "Inside the tumor, resident cDC1s are the primary source of CXCL9 and CXCL10 which modulate the recruitment of effector T cells." (PMID 36230990, 2022). "Similar results were obtained with entolimod or imiquimod, two agonists of TLR5 and TLR7, respectively, which triggered a CD8 T-cell chemoattraction through an INFγ-CXCL9/10 pathway and colon or vaginal tumor growth delay." (PMID 36429101, 2022). "CXCL9 released by tumor cells can regulate the enrichment of NK cell subset that expresses tumor necrosis factor-related apoptosis-in-ducing ligand (TRAIL+NK cell) to tumor tissues." (PMID 33854600, 2021). "DCs also play an important role at the tumor site where, through the secretion of CXCL9 and CXCL10, cDC1s contribute to the recruitment and restimulation of T cells." (PMID 34062821, 2021). "At tumor sites, eosinophils repolarize macrophages, normalize tumoral blood vessels, and recruit and activate tumor-specific cytotoxic T cells via a CXCL9/CXCL10-dependent mechanism." (PMID 33754022, 2021). "Loss of CXCR3 or its ligands, CXCL9 or CXCL10, has been shown to disrupt the migration of adoptively transferred T cells to solid tumors resulting in impaired anti-tumor responses." (PMID 34867942, 2021). "We demonstrated a significant positive correlation between an increased level of plasma CXCL9 and the number of tumor-infiltrating CD3+ and CD8+ T cells." (PMID 33723260, 2021). "On the other hand, CXCL9 can act directly on tumor cells expressing the CXCR3 receptor to promote cell migration and epithelial mesenchymal transition." (PMID 33815462, 2021). "Consistently, the expression of CXCL9 was significantly negatively correlated with the tumor purity in multiple cancer types." (PMID 35052427, 2021). "Inhibition of miR-21 in TAMs reduced tumor growth by inducing proinflammatory immune responses, including TNF, CXCL10, and CXCL9; this activates CD8+ T cells and causes the secretion of cytokines and chemokines, including IL-12 and CXCL10." (PMID 34827646, 2021). "The results showed that in tumor, the expression of CXCL9 negatively correlated with tumor stage, nodal and distant metastases, and Dukes’ stage (p = 0.01, p = 0.005, p = 0.005), but not with the other three chemokines (data not shown)." (PMID 34539647, 2021). "TIM3 also expressed by DC negatively regulates IFN-α production by pDC and CXCL9 production by cDC1 limiting the recruitment of cytotoxic T cells into the tumor." (PMID 33418996, 2021). "CXCL9 predominantly mediates lymphocytic infiltration to the focal sites and suppresses tumor growth." (PMID 34054929, 2021). "A possible explanation is that the attenuation of the CD8 T cell function by Ezh2 inhibition is overcome by DNMT inhibitor induced immunostimulatory factors, such as CXCL9 and 10, in the tumor microenvironment." (PMID 33403469, 2021). "Th1 cells recruitment at tumor site can be enhanced by the epigenetically induced re-expression of endogenous retroviruses or Th1-attracting chemokines (CXCL9 and CXCL10) by tumor cells." (PMID 34262562, 2021). "Four cell types, SELENOP+M4, CXCL9+M2, CD1C+DC1, and CLEC9A+DC2, were negatively associated with tumor progression (FDR < 0.05)." (PMID 34659209, 2021). "Along the same lines, other studies have linked increase of cytokines, like CXCL9, CXCL10, CXCL11, and CXCL19, under ICIs as a sign of enhanced general immune reactivity with both subsequent tumor responses and development of irAE in NSCLC." (PMID 34268127, 2021).
tumor (continued). "Second, we examined gene expression levels for a selection of chemokines associated with T cell recruitment to the tumor, namely CCL4, CCL5, CXCL9, CXCL10." (PMID 33806316, 2021). "Previous studies have shown that CXCL9 is a favourable prognostic biomarker in patients with solid malignancies and a predictor of better response to anti-PD-1 therapy, while its tumour-promoting effect has also been reported in diffuse large B-cell lymphoma." (PMID 34527583, 2021). "CXCL9 expression was negatively correlated with tumour purity (r=-0.416, P<0.01) in BC as well as its subtypes." (PMID 34527583, 2021). "CXCL9 and CXCL10 had functions in the tumor microenvironment, such as regulating T cell differentiation and directing the migration of immune cells to tumor tissues, while CCL5 was thought to be associated with graft-versus-host disease." (PMID 34727927, 2021). "Results showed that the expression of CXCL9 was negatively correlated to tumor purity, and positively correlated to the levels of immune cells, including B cells, CD8+T cells, CD4+T cells, macrophages, neutrophils, and dendritic cell." (PMID 33854600, 2021). "In our study, LS tumor budding cases from TCGA demonstrated significantly higher CXCL9 expression compared to HS patients suggesting that M1 macrophages are a key cellular source of CXCL9 in PDAC." (PMID 33806316, 2021). "As an IFN-γ inducible chemokine, CXCL9 is a significant mediator of interaction between the host and tumor." (PMID 33815462, 2021). "Tumors expressing CXCL9 deficiency fail to recruit cytotoxic CD8 T cells, resulting in accelerated tumor growth." (PMID 33854600, 2021). "Tumor-bearing mice had significantly elevated hepatic expression of the pro-inflammatory cytokines IL-1α, IL-1β, TNF-α, Cxcl9, and Cxcl10 compared to tumor-free mice." (PMID 34445729, 2021). "These M1 macrophages induce myeloma tumor cell death by activation of the intrinsic apoptotic pathway, and secrete CXCL9 and CXCL10, two angiostatic chemokines that contribute to the control of tumor development." (PMID 33435306, 2021). "CXCL9 (fold change = 8.1) is a chemokine mainly produced by monocytes, epithelial cells, fibroblasts, and tumor cells, which attracts T lymphocytes to the infection site." (PMID 33897690, 2021). "It has been reported that CTCs with higher CXCR3 expression can be recruited to the tumor site by ligands, including CXCL9, CXCL10, and CXCL11, which are known as IFNγ-inducible chemokines." (PMID 34539647, 2021). "Clonal tumor mutation burden (TMB) was the strongest predictor of CPI response, followed by total TMB and CXCL9 expression." (PMID 33508232, 2021). "Consistent with all above the results, immune-related genes were highly expressed in hot tumor, for instance, CXCL9, TCL1A, CCL19, CXCL13, MS4A1, and C4orf7." (PMID 33816503, 2021). "Elevated levels of the chemokines, such as CXC-chemokine ligand 9 (CXCL9) and CXC-chemokine ligand 10 (CXCL10) are reportedly associated with the increased number of tumor-infiltrating CD8+ T cells." (PMID 33809707, 2021). "In the tumor microenvironment, the CXCL9/10/11-CXCR3 signaling pathway is known to primarily promote the chemotactic movement of CXCR3-activated immune cells into the tumor site for antitumor immunity." (PMID 33547412, 2021). "In particular, several crucial chemokines and receptors (CXCL9, CXCL10, and CXCR3), which can recruit CD8+ T cells into the tumor microenvironment, were upregulated in the high-risk group." (PMID 34961815, 2021). "Initially, we analyzed the relationship between CXCLs and HNSC stage and found that CXCL9–12 and 14 were differentially expressed in different tumor stages." (PMID 34247149, 2021). "High expression of CXCL9 accelerated the generation of CCL5 in tumor microenvironment, and tumors with elevated expression of CXCL9 and CCL5 showed higher immunoreactivity and immune checkpoint inhibition response." (PMID 33854600, 2021).